CD4 (CD4 molecule)
Diseases named in the same sentence as CD4 in open-access papers (continued):
Sharing a sentence is not in itself a finding about the gene and the disease.
celiac disease (continued). "In patients affected by the celiac disease, the passage of gliadin peptides by the intestinal submucosa through transferrin receptors CD71 acts by activating CD4+ T lymphocytes, which recognize these peptides through T cell receptors." (PMID 30254638, 2018). "CD4 were lower in NCGS than controls and celiac disease (31.0 ± 22.1, 72.5 ± 29.5, and 103.7 ± 15.7 cells/mm2; p < 0.001)." (PMID 29362561, 2017). "In contrast with observations in celiac disease, the frequency of γδT IEL was low in both OIE and AIE, while the frequency of CD4+ IEL was often high in OIE." (PMID 26101883, 2015). "In peripheral blood, CD38 expression on pre-activated CD62Llow CD4+ T cells correlates with CCR9 and particularly with β7-integrin expression, and gliadin-specific CD4+ T cells from patients with celiac disease are homogenously CD38+." (PMID 25938500, 2015). "Especially, the gluten-specific CD4+ T cells are known to express CXCR3, responding to the CXCL9 and CXCL10 that are expressed in the coeliac regions, for which CXCL9 and CXCR are suggested as the therapeutic targets for the coeliac disease." (PMID 39897058, 2025). "Similarly, when an enteroadherent strain of Escherichia coli from a celiac disease patient was administered to clean SPF mice, they exhibited higher IELs counts and gliadin-specific CD4+ T-cell proliferation after gluten challenge." (PMID 38396767, 2024). "The increased IELs in celiac disease are CD3+ T-cells of CD4− CD8+ TCRαβ and CD4− CD8− TCRγδ phenotypes, but some cells also express CD94/NKG2D, whilst lymphocytes in the lamina propria are mainly CD4+ CD8−." (PMID 35626087, 2022). "CD4+ T cells reactive to these epitopes can only be found in the intestinal tissue of celiac disease patients, and not in controls including non-celiac gluten-intolerant patients." (PMID 33796112, 2021). "Also, CD4+, CD25+, alpha-beta regulatory T cell differentiation are identified as prominent biological terms in the celiac disease patients." (PMID 34466507, 2019). "The differentiation of pathogenic, rather than regulatory, CD4+ T cells is thought to be induced by proinflammatory cytokines, including IL-15 and IFN-α, that are present in the intestinal mucosa from celiac disease patients." (PMID 21949668, 2012). "In conclusion, we show that Dextramers to detect α-gliadin-specific CD4+ TEM can accurately identify most celiac disease patients irrespective of the use of a (self-initiated) GFD and that this test is methodologically feasible in a specialized laboratory setting." (PMID 40778297, 2025). "Also, the staining reactions were strong in dual-colour indirect immunofluorescence staining of CD3+CD8− IELs and in an immunohistochemical panel (CD4, CD8, CD19, CD163, and FOXP3) consisting of markers known to be relevant for the pathogenesis of coeliac disease." (PMID 31730447, 2019).
schistosomiasis (95 papers, 2007 to 2025). An infectious disease caused by parasitic trematodes of the genus Schistosoma that colonize human blood vessels and release eggs that can cause granulomatous reactions leading to acute (swimmer's itch or acute schistosomiasis syndrome) or chronic disease. "In summary, this study identified restrictive immunodominance as a key pathogenic component of schistosomiasis and other CD4+ T cell-mediated diseases." (PMID 39661861, 2024). "Immunodominance is an important pathogenic component that influences CD4+ T cell modulation in experimental murine schistosomiasis." (PMID 39661861, 2024). "Schistosomiasis is a major helminthic disease in which damage to the affected organs is orchestrated by a pathogenic host CD4 T helper (Th) cell-mediated immune response against parasite eggs." (PMID 30761125, 2019). "At the cellular level, schistosomiasis has been associated with increased expression of CD4+ T cell parameters that enhance HIV susceptibility, including increased CCR5+ expression and a Th17 phenotype." (PMID 31798936, 2019). "In the current study, to investigate the impact of CD4+CD25+Treg cells on vaccines against schistosomiasis, we have chosen a plasmid encodingSj26GST as a DNA vaccine." (PMID 22802961, 2012). "Schistosomiasis and some helminth infections are known to induce systemic inflammation associated with increased activation of CD4 cells and higher levels of CD8 cells, including surface receptor expression." (PMID 19852800, 2009). "The importance of CD4+ T helper cells in the response to schistosomiasis, and the role of HLA class II alleles in recruiting these, suggests that variation in the HLA region may play an important role in control of schistosome infections." (PMID 33659002, 2021). "Schistosoma blood flukes, which cause schistosomiasis affecting 200 million people in the world, are dependent on signals from host CD4+ T cells to facilitate parasite growth and development in the mammalian host and to induce Th2-biased inflammatory granulomas." (PMID 23349889, 2013). "Weakly significant signals for the associations of schistosomiasis with an increased viral load, reduced CD4+ (CD = cluster of differentiation) T cell count, and a reduced CD4+/CD8+ ratio could be observed but was inconsistently lost in the case of the stratification on the species complex level." (PMID 35890001, 2022). "Weakly significant signs of potential associations between schistosomiasis and unfavorable factors, such as a high viral load and reduced CD4+ T cell count, have to be considered as hypothesis-forming only and should be re-assessed by sufficiently powered prospective studies." (PMID 35890001, 2022). "In particular, a recently growing number of studies have indicated that IL-17, a CD4+ T cell-derived cytokine, is most directly associated with the severity of hepatic granulomatous inflammation, suggesting that IL-17-producing T cells are a major force behind severe pathology in schistosomiasis." (PMID 22102924, 2011). "Schistosomiasis, a major neglected tropical helminthic disease infecting 200 million people with an estimated 600 million at risk worldwide, is an excellent model for studying the induction and regulation of differentiation of the various CD4+ T cell subsets in response to infection." (PMID 22102924, 2011). "The immune response and immunopathology of schistosomiasis stem from CD4+ T-cell reactivity to egg antigens." (PMID 40365538, 2025). "This suggests that the failure to modulate, and consequently, the development of high pathology in murine schistosomiasis, depends on the CD4+ T cell response to one major dominant epitope." (PMID 39661861, 2024). "While PA alone did not significantly impact PD1 expression, it effectively countered the schistosomiasis-induced alteration of CD4+ T cell populations." (PMID 39959586, 2024).
schistosomiasis (continued). "This study examined the correlation between immunodominance of the major egg antigen Sm-p40234-246, a robust Th1/Th17 anti-egg CD4 T-cell response, and severe liver immunopathology in experimental murine schistosomiasis." (PMID 39661861, 2024). "A study in Brazil, a country considered endemic for schistosomiasis, suggested that Sm14 protects uninfected individuals against schistosomiasis by stimulating CD4+ T cells and producing higher IFN-γ and TNF-α." (PMID 39481080, 2024). "This study demonstrated that restrictive immunodominance significantly influences the severity of murine schistosomiasis by modulating the CD4+ T cell response to a single dominant egg epitope, Sm-p40234-246." (PMID 39661861, 2024). "Focusing on HIV-specific infection- and immune parameters, tendencies of a higher viral load, lower CD4+ T cell count, and lower CD4+/CD8+ ratio with schistosomiasis were observed." (PMID 35890001, 2022). "CD4+ T cell-mediated Th1 and Th2 responses play an important role in against infection and immunopathogenesis of schistosomiasis." (PMID 35584107, 2022). "Since S. japonicum infection induces high levels of PD-1 expression in CD4+ and CD8+ T cells and impairs T cell proliferation, we aimed to generate PD-1-deficient mice and analyze the impact of PD-1 deficiency on schistosomiasis." (PMID 35666747, 2022). "The involvement of T lymphocytes, especially CD4+ T cells, in the immune response against schistosomiasis is essential." (PMID 35839247, 2022). "Studies assessing the pathogenesis of schistosomiasis demonstrate the role of CD4+ T cells in the formation of hepatic granulomas." (PMID 33815321, 2021). "In this study, we identified the complex network of cytokines expressed by CD4+T lymphocytes in individuals with periportal fibrosis secondary to schistosomiasis who reside in an endemic area." (PMID 33692784, 2021). "In human schistosomiasis, IL17 producing CD4 T helper cells are associated with ultrasound textural abnormalities while T regulatory cells are associated with reductions in this pathology." (PMID 33659002, 2021). "The aim of this study was to evaluate the CD4+ T lymphocyte profile of patients with different degrees of periportal fibrosis secondary to schistosomiasis." (PMID 33692784, 2021). "To investigate the contribution of Th1, Th2, and Th17 cytokines, we analyzed the intracellular expression of these molecules in CD4+ T lymphocytes from individuals with periportal fibrosis secondary to schistosomiasis." (PMID 33692784, 2021). "Schistosomiasis is one of the world’s major public health problem in terms of morbidity and mortality, which is characterized by a marked egg-induced CD4+ T cell programmed inflammation and subsequent fibrosis." (PMID 32503644, 2020). "As reported, adaptive CD4+ T cells are highly involved in immunopathology and the regulation of inflammation in schistosomiasis." (PMID 32894174, 2020). "The immune response and immunopathology of schistosomiasis are a consequence of CD4+ T-cell sensitization to egg antigens." (PMID 32132991, 2020). "As one of the major participants, CD4+ T cells played an imperative role in the regulation of immunopathology in schistosomiasis." (PMID 33124146, 2020). "Another limitation of our enrollment design is the inability to compare CD4 T cell profiles in SM+ individuals before and after treatment for schistosomiasis." (PMID 32117277, 2020). "Numerous studies have shown that CD4+ T cells are the predominant contributors to inflammatory responses and the regulators of hepatic granuloma and fibrosis in schistosomiasis." (PMID 32894174, 2020). "CXCR5+ follicular regulatory (Tfr) cells, an especially-classified thymic-derived Foxp3+ Tregs, are reported to increase within CD4+ T cells and total Tfh cells in schistosomiasis patients." (PMID 32894174, 2020).
schistosomiasis (continued). "CD4+ T cells play an important role in the pathogenesis of schistosomiasis, which differentiate into T helper (Th) cell type 1/Th2 subsets after being stimulated by schistosoma antigen." (PMID 32295161, 2020). "During schistosomiasis, the response to schistosome antigen is primarily mediated by activated CD4+ αβ T cells." (PMID 32132991, 2020). "As we know, T cells, especially CD4+ Th cells play important roles in the process of Schistosomiasis." (PMID 31775660, 2019). "Secor and colleagues reported elevated expression of CCR5 and CXCR4 on circulating CD4 T cells of S. mansoni-infected Kenyan men, and their expression dropped after schistosomiasis treatment." (PMID 31798936, 2019). "The most serious schistosomiasis immune pathogenesis is the hepatic granuloma formation around deposited eggs and subsequent fibrosis, which are orchestrated by the CD4+ T cell response." (PMID 30116754, 2018). "In patients with schistosomiasis, proportion of CD4+ memory T cells was significantly lower than in uninfected people." (PMID 29795573, 2018). "The effect that multiple percutaneous exposures to Schistosoma larvae has on the development of early CD4+ lymphocyte reactivity is unclear, yet it is important in the context of humans living in areas where schistosomiasis is endemic." (PMID 25624353, 2015). "Generally, the studies of protective mechanisms against schistosomiasis are concentrated on CD4+T cells and antibody responses." (PMID 26714844, 2015). "In addition, these novel findings imply that AQP4 may function as a new therapeutic target if it is directly involved in Th polarization pathways within immune system cells by modulating CD4+ T cell responses for schistosomiasis or other immune-associated diseases." (PMID 25604731, 2015). "In the group with CD4+ cell counts higher than 500 cells/μl the seroprevalence was higher for those on HAART therapy for all helminths except for schistosomiasis." (PMID 25188395, 2014). "The presence of IL-17-secreting CD4+ T (Th17) lymphocytes correlates with severe hepatic pathology in murine schistosomiasis." (PMID 24637903, 2014). "In human schistosomiasis, although praziquantel treatment leads to a significant decline in CD4+ memory T cell proportions, there is a pronounced increase in CD4+ memory cell replication." (PMID 23415733, 2013). "Unfortunately, the roles of the unique CD4+ T cells described here upon the pathology of schistosomiasis are still unclear, as a method to specifically deplete or isolate these cells has not been established." (PMID 24358216, 2013). "The impact of CD4+CD25+Tregs on vaccines against schistosomiasis, a neglected tropical disease thatis a major public health concern, however, has not been examined." (PMID 22802961, 2012). "In schistosomiasis patients, parasite eggs trapped in hepatic sinusoids become foci for CD4+ T cell-orchestrated granulomatous cellular infiltrates." (PMID 22291593, 2012). "It was found that the major egg antigens have noticed desensitizing role to the CD4+ Th cells that mediate granuloma formation, and therefore ameliorate the clinical signs of schistosomiasis." (PMID 23071694, 2012). "In murine schistosomiasis, the pathology is induced by a CD4+ Th2-driven granulomatous response directed against schistosome eggs lodged in the host liver." (PMID 22545160, 2012). "Instead of promoting Th2 disease, our data suggest that macrophage-specific Arg1 contributes to the resolution of schistosomiasis by inhibiting CD4+ T cell effector function." (PMID 19360123, 2009). "Although it is generally agreed that a successful schistosomiasis vaccine will have the generation of an antigen-specific CD4+ T cell response, it is still unclear which subset of CD4+ T cells, Th1 or Th2, should be induced." (PMID 19419545, 2009).
schistosomiasis (continued). "Although vRNA loads were higher in animals with schistosomiasis, levels of both CD4+ and CD8+ T cells were also elevated in these animals compared to virus-only controls, consistent with the generalized immune activation caused by schistosomiasis." (PMID 18648516, 2008). "The immunopathology in schistosomiasis is mediated by CD4 effector T cells." (PMID 39439825, 2024). "According to this rationale, the primary difference between schistosomiasis and diseases resulting from a "rogue" CD4+ T-cell response is the location of the target epitope, whether in the liver, pancreas, skin, intestine, or brain." (PMID 39661861, 2024). "These cellular changes were accompanied by a significant reduction in Th2 cytokines IL-4 and IL-5 in Cre+ MGL2+ CD11b+ cDC2 depleted mice, as a proportion of CD4+ T cells, implicating Irf4-dependent dependent cDC2s as critical in promoting type-2 responses during pre-patent schistosomiasis." (PMID 37012228, 2023). "In conclusion, the Sjp90α-derived peptides of S. japonicum were exclusively identified, and the Sjp90α-1 peptide was found to induce CD4+ T-cell differentiation through promoting DC activation, which enriched our understanding of the immunopathogenesis of schistosomiasis." (PMID 36364989, 2022). "As CD4+ T cells orchestrate the development of immunopathology in schistosomiasis, we investigated whether the immunopathology change resulted from the Th1/Th2 dominance." (PMID 32503644, 2020). "Therefore, the IL-17-producing CD4+ T-cell population driven by IL-23 was recognized as a separate lineage and designated as Th17 cells that contribute to severe immunopathology in schistosomiasis." (PMID 32132991, 2020). "Along these lines, other population-based studies demonstrated that schistosomiasis has been linked to an increase in HIV infection due to increased concentrations of CD4-positive cells in semen of men with schistosomiasis compared to men who had been cleared of the infection." (PMID 30634429, 2019). "The hepatic inflammation is mediated by CD4 Th cells specific for egg antigens, making schistosomiasis an immunologically mediated disease, since the damage to the affected tissues is largely inflicted by the host's own immune system rather than by the parasite itself." (PMID 30761125, 2019). "CD4+ T cells play an important role in the pathogenesis of schistosomiasis." (PMID 31623153, 2019). "Schistosomiasis is an immunopathogenic disorder in which CD4+ T cells play key roles." (PMID 31623153, 2019). "As CD4+ T cells orchestrate the development of immunopathology in schistosomiasis, we first investigated whether CD4+ T cells were regulated after pioglitazone treatment during S. japonicum infection." (PMID 30116754, 2018). "HIV+ individuals with delayed schistosomiasis treatment have increased viral loads and lower CD4 T-cell counts compared to those who received early treatment, and antihelminthic drugs may act to reduce viral load and increase CD4 levels." (PMID 30543654, 2018). "Interestingly, the interplay between alternatively activated macrophages and Th2 CD4+ T cells has been evaluated in the context of schistosomiasis." (PMID 30090103, 2018). "However, the presence of CD4+ T cell memory response in chronically infected individuals with schistosomiasis and the kinetics of these cells is poorly understood." (PMID 29449839, 2017). "Using the mice model of schistosomiasis, the present study also indicated that Bcl-6+CD4+ cells would express higher CXCR5 of Tfh marker molecules than Bcl-6−CD4+ cell, the ability of Bcl-6 to up-regulate the expression of CXCR5 was strengthened in mice following S. japonicum infection." (PMID 29192177, 2017). "For those members in the control and schistosomiasis groups for whom we had CD3+ CD4+ CD25hi T-regulatory cells percentages at each time point we looked to see if those levels changed significantly between time points using the Freidman test followed by Dunn’s multiple comparison test." (PMID 27926921, 2016).